PNO1 (partner of NOB1 homolog)
Diseases named in the same sentence as PNO1 in open-access papers (continued):
Sharing a sentence is not in itself a finding about the gene and the disease.
osteosarcoma (1 paper, 2023). A usually aggressive malignant bone-forming mesenchymal neoplasm, predominantly affecting adolescents and young adults. "Third, we verified that PNO1 influenced osteosarcoma via TGF-β and YAP/TAZ signaling pathways, but the level of change in the related proteins was not consistent." (PMID 38071381, 2023). "Down-regulation of PNO1 inhibited the proliferation, migration, and invasion, and induced cell apoptosis and cell cycle arrest of osteosarcoma cells." (PMID 38071381, 2023). "In order to expound the oncogenic mechanisms of PNO1 in osteosarcoma, transcriptome sequencing and bioinformatic analysis was used in our study." (PMID 38071381, 2023). "Taken together, this study verifies the tumor promoting effect and mechanisms of PNO1 in osteosarcoma." (PMID 38071381, 2023). "In this study, we aimed to examine the PNO1 expression in osteosarcoma samples, explore the effect of PNO1 in vivo and in vitro." (PMID 38071381, 2023). "Analysis results demonstrated that the over-expression of PNO1 acted as contribution in malignant progression of osteosarcoma." (PMID 38071381, 2023). "In the current study, we found the found the increased expression of PNO1 in osteosarcoma tissues and cell lines." (PMID 38071381, 2023). "This study aimed to explore the potential role and mechanisms of the partner of NOB1 homolog (PNO1) in osteosarcoma." (PMID 38071381, 2023). "Wound-healing and Transwell assays were used to investigate whether PNO1 knockdown would affect the migration and invasion abilities in osteosarcoma cells." (PMID 38071381, 2023). "Western blotting was adopted to investigate the expression of PNO1 in osteosarcoma." (PMID 38071381, 2023). "Therefore, further molecular studies are still necessary to explore the complex regulatory function of PNO1 in osteosarcoma." (PMID 38071381, 2023). "Overall, these results indicated that PNO1 could regulate the progression of osteosarcoma cells via TGF-β and YAP/TAZ signaling pathway." (PMID 38071381, 2023). "The expression of PNO1 was higher in osteosarcoma tissues than that in adjacent tissues." (PMID 38071381, 2023). "In this research, we explained the oncogenic function and mechanisms of PNO1 in osteosarcoma." (PMID 38071381, 2023). "Meanwhile, the levels of TGFB2, p-Smad2, p-Smad3, and BMP-6 showed a reverse trend after the SRI-011381 application, suggesting that PNO1 could influence the progression of osteosarcoma cells via the TGF-β signaling pathway." (PMID 38071381, 2023). "PNO1 could contribute to malignant progression of osteosarcoma by activating TGF-β pathway and suppressing BMP pathways." (PMID 38071381, 2023). "In addition, according to the transcriptome sequencing and bioinformatics analysis, we elucidated the oncogenic mechanism of PNO1 in osteosarcoma cells." (PMID 38071381, 2023). "All these results suggested the tumor promoting function of PNO1 in osteosarcoma." (PMID 38071381, 2023). "However, the study regarding the function and mechanisms of PNO1 in osteosarcoma is limited." (PMID 38071381, 2023). "PNO1 may alter the progression of osteosarcoma via TGF-β and YAP/TAZ signaling pathways." (PMID 38071381, 2023). "Furthermore, according to transcriptome sequencing and Kyoto Encyclopedia of Genes and Genomes pathway analysis, we found that PNO1 might affect the progression of osteosarcoma via TGF-β and YAP/TAZ signaling pathways." (PMID 38071381, 2023). "PNO1 could be a potential target for osteosarcoma treatment." (PMID 38071381, 2023). "However, the regulatory function and mechanisms of PNO1 in osteosarcoma were poorly known." (PMID 38071381, 2023). "We selected two osteosarcoma cell lines MNNG-HOS and U2OS to investigate the role of PNO1." (PMID 38071381, 2023). "However, due tot he relatively small sample size and the lack of follow-up information, the predictive values of PNO1 for osteosarcoma were not investigated." (PMID 38071381, 2023).
ovarian carcinoma (1 paper, 2025). A malignant neoplasm originating from the surface ovarian epithelium. "Similarly, regulators of RNA processing and splicing such as TCEA1, SF3B6, ZCRB1, PNO1, and DCAF13 were overexpressed, indicating dysregulation of mRNA metabolism and splicing fidelity in ovarian cancer." (PMID 41228302, 2025).
ovarian insufficiency (1 paper, 2020). "Interestingly, a set of 5 proteins (KHDC3L, SRSF8, PNO1, RASIP1, and MORC2) exhibited a significant association with ovarian insufficiency in this cohort." (PMID 32410729, 2020).
tumor (11 papers, 2020 to 2025). "We further investigated the differential prognosis between high and low expression levels of PNO1 in three high-risk relapse subgroups: tumor size ≥ 3 cm, high serum AFP level, and more positive rate of Ki-67." (PMID 34050137, 2021). "First, GSEA indicated that PNO1 was positively associated with tumor cell proliferation." (PMID 32483111, 2020). "The tumor-suppressive function of EBF1 is primarily attributed to its negative regulation of partner of NOB1 (PNO1), an oncogene involved in ribosome biogenesis." (PMID 40508012, 2025). "Deregulated PNO1 also inhibited tumor growth in vivo and decreased the number and confluency of TNBC cells in vitro." (PMID 38609711, 2024). "The result showed that, compared with adjacent tissue samples, the tumor tissues displayed a higher expression level of PNO1." (PMID 38071381, 2023). "As expected, SLC7A11 was positively correlated with PNO1 expression in HCC tumor tissues (p < 0.05)." (PMID 36446769, 2022). "Further analysis showed that the suppression of PNO1 increases the sensitivity of tumor cells to ferroptosis by inhibiting autophagy." (PMID 36446769, 2022). "High PNO1 expression was an independent risk factor in the poor HCC prognosis patients and significantly related to clinicopathological features, such as tumor size, AFP level, and positive rate of Ki-67." (PMID 34050137, 2021). "Our results unraveled a novel function of PNO1 in tumor cells and can thus serve as a new therapeutic strategy for targeting PNO1 in HCC." (PMID 34050137, 2021). "Using 150 formalin-fixed and paraffin-embedded samples and 8 fresh samples, we found high PNO1 expression in HCC tumor tissues through Western blotting and RT-PCR." (PMID 34050137, 2021). "Then, we further probed the differential prognosis between LUAD patients with high or low PNO1 expression in two poor prognosis subgroups: tumor size > 3 cm and TNM stage III disease." (PMID 32483111, 2020). "The expression level of PNO1, particularly localized in the nucleus of tumour cells, correlates with high grade (P = .0091)." (PMID 31800162, 2020). "Our results confirmed that in a mouse model, the PNO1 KD cells formed significantly smaller and lighter tumours than the control cells, further confirming the involvement of PNO1 in tumour growth in vivo." (PMID 31800162, 2020). "In accordance with the cellular functional study results, IPA analysis confirmed that several apoptosis‐related functions were enhanced in PNO1 KD cells, while neoplasia, growth and proliferation of tumour cells were inhibited." (PMID 31800162, 2020). "In contrast, only 16 out of 52 (30.8%) cases with a tumor size ≤ 3 cm exhibited high PNO1 expression (P = 0.009)." (PMID 32483111, 2020). "Both bioinformatics databases and tumor tissues demonstrated that the expression of PNO1 in LUAD tissues was higher than that in adjacent tissues and predicted poor survival in LUAD patients." (PMID 32483111, 2020). "We then analysed the correlation between clinicopathological parameters and PNO1 expression in the 56 tumour tissue samples." (PMID 31800162, 2020). "PNO1 also had great regulatory function in tumor metabolism." (PMID 38071381, 2023). "The expression of PNO1 in tumor and adjacent tissue samples was examined using western blotting." (PMID 38071381, 2023). "All these results suggested that PNO1 itself may operate as a redox-responsive suppressor and that its inhibition can promote ferroptosis to limit tumor growth in HCC cell lines." (PMID 36446769, 2022). "The findings demonstrated that PNO1 was overexpressed in HCC tumor tissues (p < 0.05)." (PMID 34050137, 2021). "Results revealed that PNO1 expression was higher in tumor tissue than in adjacent normal tissue." (PMID 34050137, 2021). "Notably, high PNO1 expression was marginally significantly related with tumor size (p = 0.042), serum alpha-fetoprotein (AFP) level (p = 0.006), and positive rate of Ki-67 (p = 0.013)." (PMID 34050137, 2021).
tumor (continued). "The staining of PNO1 was low or moderate in low‐grade tumours, but strong in high‐grade tumours." (PMID 31800162, 2020). "We found that the expression level of PNO1 was closely correlated with tumor size and TNM stage." (PMID 32483111, 2020). "Tumor weights were significantly lower in the sh-PNO1 group than in the sh-Ctrl group." (PMID 32483111, 2020). "In total, 37 out of 68 (54.4%) cases with a tumor size >3 cm showed high PNO1 expression." (PMID 32483111, 2020). "Therefore, EMT modulation by PNO1 knockout will inhibit metastasis in addition to tumour growth." (PMID 38722284, 2024). "However, the role of PNO1 in tumor progression and its specific regulatory mechanism remain unclear." (PMID 34050137, 2021). "Thus, further research may focus on the potential of PNO1 as a prognostic biomarker and the function of PNO1 as an oncogene in tumor progression." (PMID 32483111, 2020). "Besides this, the functions of chemotaxis, cell movement, and migration and invasion of tumour cells were also down‐regulated in PNO1 KD cells, indicating that PNO1 might also participate in the metastasis of cancer cells." (PMID 31800162, 2020). "Collectively, the preclinical data reported herein provide a promising strategy for treating HCC patients whose tumours harbour higher PNO1 expression and constitutively active Notch signalling pathway." (PMID 38722284, 2024). "Pan’s study suggested that PNO1 could be used as a therapeutic target for celecoxib to inhibit HCC and induce tumor proliferation and metastasis." (PMID 34050137, 2021). "PNO1 KD inhibited the cell proliferation and colonogenesis ability, promoted cell apoptosis and reduced the tumorigenic ability of UBC, suggesting the pro‐tumour role of PNO1 in UBC." (PMID 31800162, 2020). "Then, we examined the protein expression level of PNO1 in 8 pairs of fresh LUAD tumor tissue samples and the corresponding nonmalignant tissue samples by Western Blotting." (PMID 32483111, 2020). "To further investigate the role of PNO1 in the tumor progression of LUAD, we selected two wild-type LUAD cell lines (A549 and NCI-H1299) to construct cell lines with stable PNO1 downregulation (sh-PNO1) and PNO1 upregulation (PNO1) via transfection with lentiviral plasmids." (PMID 32483111, 2020). "Celecoxib, a nonsteroidal anti‐inflammatory drug, inhibited PNO1 expression and HCC tumour growth by regulating AKT/mTOR pathway." (PMID 38722284, 2024).
cancer (10 papers, 2019 to 2024). A tumor composed of atypical neoplastic, often pleomorphic cells that invade other tissues. "Since PNO1 is highly expressed in cancer cells, it can be used as a diagnostic biomarker and also can be an attractive target for cancer therapy." (PMID 36625087, 2023). "PNO1 has been associated with cancer progression and poor survival." (PMID 36625087, 2023). "Since PNO1 is highly expressed in several cancers, it can be used as a biomarker and targeted for the effective treatment of HCC." (PMID 38722284, 2024). "The expression manner of PNO1 was specific to the malignant potential of cancer cells, suggesting its predictive potential for human cancer." (PMID 38071381, 2023). "We first examined the expression of PNO1 using the Cancer Genome Atlas (TCGA) data bank by UALCAN (The University of Alabama at Birmingham Cancer Data Analysis Portal)." (PMID 36625087, 2023). "As expected, we found that the suppression of PNO1 expression markedly decreased the viability of cancer cells and cell viability in PNO1-overexpressing cells increased relative to that in their parental cells after erastin treatment." (PMID 36446769, 2022). "Few studies have been conducted about PNO1 as a potential oncogene that promotes cancer progression." (PMID 34050137, 2021). "In contrast to the extensive research on the ribosome-related function of PNO1, little is known about the role of PNO1 in cancer cells." (PMID 32483111, 2020). "Furthermore, the strategy will also be useful in those HCC patients whose cancer relapse because inhibition of PNO1 expression suppresses CSC characteristic." (PMID 38722284, 2024). "In addition to inhibiting cancer cells, PNO1 knockout inhibited CSC growth, migration and invasion, and also markers of stem cells, pluripotency and self‐renewal and EMT." (PMID 38722284, 2024). "We and others have found the oncogenic role of PNO1 in cancer." (PMID 38722284, 2024). "Previous studies proved that PNO1, as a ribosome assembly factor, played an important role in cancer treatment and hence could be a potential target for cancer therapy." (PMID 38071381, 2023). "The oncogenic role of PNO1 in cancer has recently been reported." (PMID 36625087, 2023). "Recently, emerging evidences suggest the crucial regulation of PNO1 in human cancer." (PMID 38071381, 2023). "Finally, the GSH metabolic reprogramming triggered by PNO1 protects HCC cancer cells from ferroptosis." (PMID 36446769, 2022). "To determine whether PNO1-mediated autophagy is related to ferroptotic cell death in HCC cancer cells, we used rapamycin or CQ co-treated with erastin to verify cell viability and cell death through CCK8 and PI staining experiments." (PMID 36446769, 2022). "Therefore, exploring the possibility of PNO1 as a prognostic biomarker and fully understanding the function of PNO1 in cancer progression are crucial for LUAD patients." (PMID 32483111, 2020).
PNO1 also shares sentences with these, for which no sentence is quoted: adenocarcinoma (1 paper); Bardet-Biedl syndrome (1); Cirrhosis (1); gastric cancer (1); glioma (1); head and neck squamous cell carcinoma (1); Joubert syndrome (1); laryngeal squamous cell carcinoma (1); rectal cancer (1).